RNU2-58P (RNA, U2 small nuclear 58, pseudogene)
Gene: Small nuclear RNA gene on chromosome 17 (59,129,276 to 59,129,458, reverse strand). Ensembl gene ENSG00000252212.
Homologues: Orthologues: rat LOC120093486 (48% identical), pig U2 (36% identical), macaque U2 (32% identical), rabbit U2 (32% identical), tropical clawed frog U2 (32% identical), guinea pig U2 (28% identical), tropical clawed frog U2 (27% identical). Paralogues in human: RNU2-41P (45% identical), RNU2-10P (44% identical), RNU2-72P (43% identical), RNU2-22P (40% identical), RNU2-60P (39% identical), RNU2-24P (38% identical), RNU2-28P (38% identical), RNU2-53P (38% identical), RNU2-55P (37% identical), U2 (37% identical), RNU2-34P (36% identical), U2 (36% identical), and 65 more.